ERBB2 (erb-b2 receptor tyrosine kinase 2)
Diseases named in the same sentence as ERBB2 in open-access papers (continued):
Sharing a sentence is not in itself a finding about the gene and the disease.
osteosarcoma (144 papers, 2003 to 2026). A usually aggressive malignant bone-forming mesenchymal neoplasm, predominantly affecting adolescents and young adults. "Compared to adult cancers, the 17q21 amplicon, including TOP2A and ERBB2 genes, seems to be differentially implicated in the osteosarcoma chemoresponsiveness." (PMID 24216996, 2013). "Expression of ErbB2 in localised and metastatic osteosarcomas has been associated with poor prognosis in terms of survival, development of metastasis and response to chemotherapy." (PMID 12569382, 2003). "Epidermal Growth Factor Receptor-2, (HER2/neu; erbB2) is a membrane bound receptor tyrosine kinase that is detected in 30–60% of human and 40% of canine primary osteosarcoma (OSA) samples." (PMID 39958231, 2025). "Increased levels of ERBB2 were found in canine osteosarcoma cell lines and tissue samples compared with normal bone." (PMID 37048099, 2023). "Recent studies have identified, several genes including Apurinic/Apyrimidinic exonuclease 1 (APEX1), Myc and epidermal growth factor receptor 2 (HER2/neu, ErbB2) in osteosarcoma pathogenesis." (PMID 27058531, 2016). "Several osteosarcoma prognostic markers have been identified, such as ErbB-2, Interferon-a/b receptor and Hsp72." (PMID 26393679, 2015). "We then show that cells derived from apheretic procedures express ErbB2 at significant levels in patients with metastatic osteosarcomas in comparison with healthy stem cell donors." (PMID 12569382, 2003). "In our experiments, we found that 18% of aphereses derived from patients affected by osteosarcoma were significantly positive for ErbB2 expression; lung metastasis derived from these same patients were also positive for ErbB2 expression." (PMID 12569382, 2003). "The ErbB2 gene, encoding for a tyrosine kinase of the EGF receptor family, is overexpressed in about 30% of human osteosarcomas and its expression correlates with a poor prognosis." (PMID 12569382, 2003). "Among the markers belonging to the first group we analysed BSP and Osteocalcin; among the oncogenes described to play a role in osteosarcoma progression, we evaluated Met and ErbB2." (PMID 12569382, 2003). "ErbB2 overexpression has been demonstrated in 30% of osteosarcomas and in many other tumours such as breast, ovary, lung and gastric carcinomas." (PMID 12569382, 2003). "Our data show that ErbB2 can be a useful marker for tumour contamination in aphereses of patients affected by ErbB2-expressing osteosarcomas and that analysis of Bone Sialoprotein expression can be an alternative useful marker." (PMID 12569382, 2003). "Additionally, the proto-oncogene erbB-2, also known as Her-2, has been found to be overexpressed in canine osteosarcoma, similar to human osteosarcoma." (PMID 37235419, 2023). "The observation that osteosarcoma cells frequently express the receptor ERBB2 has led to clinical trials assessing the effectiveness of HER2 blocking by trastuzumab (NCT04616560, NCT00005033), even though it did not have any notable effect as a primary metastatic osteosarcoma treatment." (PMID 33917001, 2021). "If our data will be confirmed on larger numbers, it can be hypothesized that a similar application of Herceptin in ErbB2 overexpressing osteosarcomas could also result in treatment improvement." (PMID 12569382, 2003). "First, to understand the role of TOP2A in the osteosarcoma chemoresponsiveness, TOP2A amplicon containing also HER2/ERBB2 gene was studied in a homogeneously treated pediatric osteosarcoma tumor collection." (PMID 24216996, 2013).
osteosarcoma (continued). "Further, some gene targets already investigated in the ACT of osteosarcoma, including B4GALNT1 (encoding beta‐1,4‐N‐acetyl‐galactosaminyltransferase 1 involved in the biosynthesis of GD2), ERBB2, and EGFR, also showed low expression in osteosarcoma compared with adjacent normal tissues." (PMID 37457661, 2023). "Several studies have confirmed the expression of ERBB2 and MET in human and canine osteosarcoma." (PMID 37048099, 2023). "This absence of ERBB2 amplification in pediatric osteosarcoma is concordant with previous publications in the field." (PMID 24216996, 2013). "To identify markers suitable for detecting osteosarcoma cells in aphereses we analysed the expression of bone-specific genes (Bone Sialoprotein (BSP) and Osteocalcin) and oncogenes (Met and ErbB2) in 22 patients with metastatic osteosarcoma and six healthy stem cell donors." (PMID 12569382, 2003). "Surprisingly, there is no ERBB2 gene co-amplification and the patients harboring TOP2A amplification tend to show a worse survival, so TOP2A analyses remain a preliminary, but a good molecular approach for the evaluation at diagnosis of pediatric osteosarcoma chemoresponsiveness." (PMID 24216996, 2013).
cervical carcinoma (136 papers, 2004 to 2026). A carcinoma arising from either the exocervical squamous epithelium or the endocervical glandular epithelium. "The most significant tumor reduction of −65%, with the response still ongoing for more than a year after the data cut-off, was observed in a cervical cancer patient with ErbB2 overexpression and additional PIK3CA, AKT, and mTOR mutations." (PMID 39908697, 2025). "A 59-year-old female with metastatic cervical cancer was found to harbor an ERBB2 S310F ECD mutation detected by tissue NGS." (PMID 40178042, 2025). "In cervical cancer, in turn, the up-regulated expression of ErbB2 was linked to enhanced proliferation and migration of cancer cells." (PMID 37312040, 2023). "Among 16 patients with ERBB2-mutated cervical cancers, the response to neratinib was linked to the pS310F mutation." (PMID 36980614, 2023). "Previous studies have identified that somatic mutations of ErbB2 or ErbB3 receptors are significantly increased in cervical cancer, which provides potential therapeutic targets for patients." (PMID 35924232, 2022). "These pathways and the recurrently mutated genes involved therein, such as EP300, ARID1A, FBXW7, NFE2L2, PIK3CA, and ERBB2, were all found to be pathogenic in previous cervical cancer studies." (PMID 28390392, 2017). "Although ErbB2 overexpression has been associated with cervical cancer, its influence on HPV infection stages was previously unknown." (PMID 38370412, 2024). "Retrospective studies identified ERBB2 gene mutations in 35–6% of cervical cancers and reported that ERBB2 gene mutations may be associated with a poor prognosis." (PMID 36333792, 2022). "The loss of Erbin, a ErbB2 (v-erb-b2 avian erythroblastic leukemia viral oncogene homolog 2) interacting protein activity in cervical cancer, was reported to upsurge STAT3 phosphorylation, thus facilitating anoikis resistance and tumor invasiveness in vitro and in vivo." (PMID 33854965, 2021). "Furthermore, EP300, ARID1A, FBXW7, NFE2L2, PIK3CA, and ERBB2 have all been previously reported as pathogenic genes in cervical cancer, and we highlighted the roles of MLL2, MLL3, and CREBBP in the tumorigenesis." (PMID 28390392, 2017). "Our novel findings regarding the EGF/PI3K/AKT/MKRN1 axis leading to PTEN suppression, along with previous data on mutations in ERBB2, and PIK3CA, ultimately indicate that ERBB2- or PIK3CA-targeted drugs might be potential therapeutic treatments for cervical cancers." (PMID 26183061, 2015). "Cervical cancer, a leading cause of cancer-related mortality in women, exhibits increased sorafenib resistance due to the Cdc25A/PKM2/ErbB2 pathway, in which Cdc25A suppresses ferroptosis by dephosphorylating PKM2 and upregulating ErbB2 expression." (PMID 41169372, 2025). "In contrast, ErbB2 acts as a negative regulator in cervical cancer, where its upregulation suppresses sorafenib-induced ferroptosis via the Cdc25A/PKM2 pathway." (PMID 40846695, 2025). "Upon ErbB2 depletion, as demonstrated through Western blot, a compelling association with ErbB2-dependent modulation of the Akt and ERK pathways was revealed in these HPV-transformed cervical cancer cell lines." (PMID 38370412, 2024). "Some studies, including whole exome sequencing analysis, found that HER2 is constitutively active due to somatic mutation, amplification and the presence of HPV integration sites close to the ERBB2 gene in cervical cancer." (PMID 37372319, 2023). "Within cytoband 17q12, ERBB2 has been recognized as a potential target for treating cervical cancer." (PMID 37966613, 2023). "CDC25A inhibits autophagy-mediated ferroptosis by upregulating ErbB2 through PKM2 dephosphorylation in cervical cancer cells." (PMID 36072430, 2022).
cervical carcinoma (continued). "Cdc25A suppressed autophagy-dependent ferroptosis in cervical cancer cells by upregulating ErbB2 levels through the dephosphorylation of PKM2." (PMID 34743185, 2021). "Whole-exome sequencing of cervical carcinoma results confirmed that the ERBB2/PIK3CA/AKT/mTOR pathway was one of the major mechanisms of cervical cancer in tumorigenesis." (PMID 35070983, 2021). "Hippo/YAP signaling pathway plays a critical role in the progression of cervical cancer and can further interact with the ErbB2 and EGFR RTKs to form a positive feedback autocrine/paracrine loop." (PMID 34745942, 2021). "Cdc25A increased the resistance of cervical cancer to sorafenib, while knockdown of ErbB2 blocked these effects." (PMID 34743185, 2021). "Neratinib, an ERBB2 inhibitor, showed a confirmed objective response rate of 25% and progression-free survival of 7.0 months in 10 cervical carcinoma patients from the phase 2 SUMMIT basket trial." (PMID 35071000, 2021). "In the present study, we sought to examine the role of ferroptosis in cervical cancer, with a focus on the Cdc25A/ErbB2 axis." (PMID 34743185, 2021). "Among those, ERBB2, CD274 (PD-L1), and PDCD1LG2 (PD-L2) had amplifications that highlight the potential for clinical trials of ERBB2 inhibitors and immunotherapeutic strategies for a subset of cervical cancers." (PMID 34680987, 2021). "Research has also shown ERBB2 expression in about 5–21% of cervical cancer specimen, and treatment with lapatinib and trastuzumab inhibited tumor growth significantly in a patient-derived xenograft model for cervical cancer." (PMID 34367146, 2021). "In summary, we demonstrated that the Cdc25A/PKM2/ErbB2 axis is a crucial pathway in sorafenib-induced ferroptosis of cervical cancer cells." (PMID 34743185, 2021). "Together, the results of our study demonstrate that Cdc25A protects cervical cancer cells against autophagy-mediated ferroptosis by upregulating ErbB2 levels through PKM2 dephosphorylation." (PMID 34743185, 2021). "ErbB2, as a key protein in ErbB signaling pathway, was demonstrated to act as a poor prognostic factor in human cervical cancer and considered as a target for cervical cancer therapy." (PMID 32596357, 2020). "Novel recurrent focal amplification events in the human epidermal growth factor receptor 2 (ErbB2 or HER2) at chromosome 17q12 have also been detected in uterine cervix cancers (17%)." (PMID 31297338, 2019). "Together, these results suggested that GDF15 activated the PI3K/AKT and MAPK/ERK signaling pathways through ErbB2 in cervical cancer cells." (PMID 29636108, 2018). "A study has shown that blocking ErbB2 leads to apoptosis of cervical cancer cells." (PMID 40028476, 2025). "Ferroptosis, which is regulated by the Cdc25A/PKM2/ErbB2 pathway, may serve as a therapeutic target in cervical cancer." (PMID 38722283, 2024). "In cervical cancer, especially in ErbB2-positive cancers, inhibition of ErbB2 activation might lead to the downregulation of the viral early genes including E6 and E7." (PMID 38370412, 2024). "A study on combination therapy targeting activated ERBB2 and PIK3CA mutations in cervical cancer found that the majority of cervical tumors could benefit from existing ERBB2/PIK3CA/AKT/mTOR-targeted drugs." (PMID 35778737, 2022). "Dysregulation and sustained activation of several RTKs, including VEGFR, HER2/ErbB2, MET, EGFR, and PDGFR, as well as its downstream oncogenic cascades can lead to cervical cancer tumorigenesis, which are associated with poor prognosis and chemoresistance for cervical cancer." (PMID 39282148, 2022). "Furthermore, overexpression of Cdc25A enhanced the resistance of cervical cancer cells to sorafenib-induced ferroptosis, and the knockdown of ErbB2 blocked the effects of Cdc25A." (PMID 34743185, 2021). "As a proto-oncogene, ERBB2 is considered to be a therapeutic target for cervical cancer." (PMID 35070983, 2021). "Previous studies show that inhibition of ErbB2 induces apoptosis of cervical cancer cells." (PMID 34743185, 2021).
cervical carcinoma (continued). "Copy number alteration driven dysregulated genes, such as PI3KCA, PI3KCB, DVL3, WWTR1, and ERBB2, are believed to play an important role in regulating immune cell infiltration, which might help to predict the prognosis of cervical cancer." (PMID 34925445, 2021). "The discovery of human epidermal growth factor receptor 2 (ErbB2 or HER2) overexpression on metastatic uterine cervix cancer cells provides an opportunity for clinical trials of targeted radiopharmaceuticals in combination with DNA damage response modifying drugs." (PMID 31297338, 2019). "The tumor types with the highest incidence of ERBB2 mutations were the following: bladder (16.6%), small bowel (8.6%), ampullar (6.5%), skin non-melanoma (6.1%), and cervical cancer (5.5%)." (PMID 29941010, 2018). "However, the exact functional role of ErbB2 in cervical cancer remains elusive." (PMID 34743185, 2021). "Therefore, we investigated the function of ErbB2 in cervical cancer cell ferroptosis." (PMID 34743185, 2021). "Furthermore, GDF15 bound to ErbB2 in a protein complex in cervical cancer cells." (PMID 29636108, 2018). "Interestingly, we also demonstrate that miR-23b downmodulation is regulated by the methylation process in p130Cas/ErbB2 cells, which is in line with recently reported results in cervical cancer where several CpG islands were found to be part of the miR-23b regulatory region." (PMID 28442738, 2017). "Complementing our findings, previous studies have reported perturbations in PIK3CA, an oncogene part of the ERBB2/PI3K/AKT/mTOR pathway with a battery of druggable targets, present in over 50% of cervical tumor and cervical cancer cell lines." (PMID 36201462, 2022). "Recurrent ERBB2 fusions included ERBB2-PGAP3 in a total of three cases of gastric, colorectal, and cervical cancers and GRB7-ERBB2 in one case each of lung and cervical cancers." (PMID 36369474, 2022). "In cervical cancer cell lines, including HeLa cells, GDF-15 promotes proliferation through phosphorylation of ErbB2, a member of the epithelial growth factor (EGF) receptor, and activation of PI3K/Akt and ERK signaling pathways." (PMID 36008442, 2022). "Here, we investigated the role of ferroptosis in cervical cancer, with a focus on the Cdc25A/PKM2/ErbB2 axis." (PMID 34743185, 2021). "Quercetin exerted a synergistic effect on cisplatin-treated cervical cancer cells primarily through downregulating the protein levels of EGFR, MYC, CCND1, and ERBB2 and upregulating CASP8." (PMID 35070983, 2021). "Our results demonstrated that quercetin combined with cisplatin has a synergistic effect on cervical cancer, leading to decreased protein expression of EGFR, MYC, CCND1, and ERBB2." (PMID 35070983, 2021). "Recent studies have reported that the most frequent integration sites of HPV were in the MACROD2, MIPOL1/TTC6, TP63, ERBB2, KLF12, and RAD51B gene by next-generation sequencing (NGS) in 272 Cervical cancer patients from the BioRAIDs study [NCT02428842]." (PMID 34680987, 2021). "Li and coworkers found that ERBB2 activated downstream Myc and promoted cells proliferation by phosphorylating AKT1 and Erk1/2 in cervical cancer." (PMID 30123134, 2018). "The expression of p-ErbB2, p-AKT1, p-Erk1/2, CyclinD1 and CyclinE1 was up-regulated and the expression of p21 was down-regulated in GDF15-overexpressing and rhGDF15-treated cervical cancer cells." (PMID 29636108, 2018). "Another study in 15 cervical cancer patients from Hong Kong revealed frequently altered genes, including FAT1, ARID1A, ERBB2, and PIK3CA." (PMID 28390392, 2017).
cervical carcinoma (continued). "We implanted non-transfected or transfected human cervical cancer cells (vector, Cdc25A, Cdc25A + sh-NC, Cdc25A + sh-ErbB2) into nude mice, and 7 days later, saline or sorafenib was injected intraperitoneally every other day for 30 days." (PMID 34743185, 2021). "Our data demonstrated that GDF15 promoted the proliferation of cervical cancer cells via the up-regulation of CyclinD1 and CyclinE1 and the down-regulation of p21 through both the PI3K/AKT and MAPK/ERK signaling pathways in a complex with ErbB2." (PMID 29636108, 2018).